MARCO (macrophage receptor with collagenous structure)
Diseases named in the same sentence as MARCO in open-access papers (continued):
Sharing a sentence is not in itself a finding about the gene and the disease.
infection (continued). "Similarly, vaccinia virus (VacV) binding to MARCO on keratinocytes enhances infection of these cells in vitro." (PMID 31596239, 2019). "However, by examining histological sections of infected mice spleen, we observed a dispersed MARCO distribution in the MZ of Ghrh−/− mice 24 h post-infection, whereas WT mice still show a continuous and organized distribution of MARCO." (PMID 30333823, 2018). "Unlike in early infection, MARCO deficiency resulted in improved pulmonary fungal clearance and diminished cryptococcal dissemination during the efferent phase." (PMID 29033946, 2017). "Thus, the increased accumulation and alternative activation of CD11b+ cDC is likely a crucial mechanism by which C. neoformans exploits MARCO to promote the Th2 response and downregulate Th1 response during infection." (PMID 29033946, 2017). "It remains to be determined whether genetic variations in MARCO and CD36 alter the expression of these receptors and whether genetic polymorphisms impact the severity of infection and the persistence of Mtb over a longer time period." (PMID 28693442, 2017). "Here, we investigated whether MARCO might be involved in the innate sensing of infection with adenovirus and recombinant adenoviral vectors by macrophages, which elicit vigorous immune responses in vivo." (PMID 28765216, 2017). "Three out of fifteen genes that were significantly affected during the primary infection could be linked to an immune function (KLRJ1, MARCO, CCL20); one was upregulated and two downregulated." (PMID 28003017, 2016). "Polymorphisms within MARCO have been shown to be associated with altered susceptibility to tuberculosis in a Gambian population, whereas no relation was found between infection and polymorphisms in SR-A." (PMID 26217337, 2015). "Nine of 11 donors showed a decrease in mRNA levels of MARCO after infection with PR/8." (PMID 22396727, 2012). "When challenged with Streptococcus pneumoniae, wild type mice could clear the infection whereas the ability was impaired in MARCO−/− mice, demonstrating the role of MARCO in the innate immune response against pathogens." (PMID 20981357, 2010). "Both mouse and human MARCO can bind to N. meningitidis independently of lipopolysaccharides (LPS), suggesting that TLR-dependent induction of MARCO through innate immune stimulation enhances the recognition and uptake of pathogenic organisms, thereby contributing to host defence against infection." (PMID 40565155, 2025). "Meanwhile, anti-inflammatory factors such as TNFAIP3, NFKBIA, NFKBIZ, SOCS1, SOCS3, and IL-10 were elevated, with the reverse trends for the inflammation-inducing genes PPBP and MARCO at 38 hpi, suggesting that the pro- and anti-inflammatory responses might coexist in PAMs during YC-2020 infection." (PMID 36338035, 2022). "Mice deficient in MARCO suffer from exacerbated inflammatory response upon infection with Streptococcus, exposure to unopsonized particulate matter, ozone inhalation and ovalbumin challenge following sensitization, suggesting an anti-inflammatory role of MARCO." (PMID 25089703, 2014). "Unlike SRA, which is expressed on virtually all macrophages, MARCO is constitutively expressed on some subsets of macrophages (i.e. alveolar, peritoneal, marginal zone of the spleen, and medullary cords of the lymph nodes), and is rapidly up-regulated on others during the course of infection." (PMID 23617307, 2013). "Macrophages from MARCO defective mice also produce significantly lower levels of pro-inflammatory cytokines than wildtype macrophages in response to infection with virulent M.tb and identify MARCO might be the additional co-receptors required for TLR-signaling in macrophage response to M.tb and TDM." (PMID 21886847, 2011). "In addition the meninges showed an increase of MARCO expression after NM infection." (PMID 21299846, 2011).
infection (continued). "Collectively, these studies reveal that CHIKV RNA accumulates in 2 subsets of LECs during the first 24 hours of infection and suggest that CHIKV interactions with MARCO are important for viral capture and internalization by endothelial cells in the LN." (PMID 38194268, 2024). "Previously, using confocal microscopy and scRNA-Seq analysis of dLN cells, we discovered that MARCO+ LECs lining the medullary sinuses internalize virus particles and harbor CHIKV RNA at 24 hours after infection." (PMID 38194268, 2024). "By 16 hours after infection, chemokine expression was increased in both WT CHIKV–infected WT and MARCO–/– mice in comparison with mock-infected mice; however, Ccl2, Cxcl1, and Cxcl9 expression remained significantly higher in the dLN of WT mice." (PMID 38194268, 2024). "Here, we found that, during the first 24 hours of infection, CHIKV RNA accumulated in MARCO-expressing lymphatic endothelial cells (LECs) in both the floor and medullary LN sinuses." (PMID 38194268, 2024). "Numerous host proteins were upregulated upon infection with Francisella, ranging from immune-related proteins to metabolic enzymes, including notably IRG1, MARCO, Rilpl2, C3, PcgF5, MT1, TRAF1, GBP2 and Fas." (PMID 38565565, 2024). "Yet, infection of CD200R1 KO PCLS with live CHA and simultaneous inhibition of MARCO significantly decreased IL6 expression compared to live CHA-infected CD200R1 KO PCLS with functional MARCO signaling." (PMID 33250899, 2020). "And in the present study, MARCO-expressing AMs and MPI cells also exhibit a robust IL-1α response upon infection with Ads." (PMID 28765216, 2017). "While the role of MARCO in modulation of adaptive immunity to fungi remains unclear, a previous study by our group demonstrated that another scavenger receptor, scavenger receptor-A (SR-A), can be exploited by C. neoformans to support Th2 immune polarization during infection." (PMID 29033946, 2017). "That splenic infection was maintained in mice depleted of CD169+ cells was unsurprising, as MuHV-4 productively infects CD169− MARCO+ splenic MZMs." (PMID 25872742, 2015). "Previous work in mouse models also showed upregulation of MARCO genes after BCG infection and a low proinflammatory response of MARCO-/- mice in response to infection with virulent MTB." (PMID 24885723, 2014). "Four days after i.p. infection of WT mice, eGFP was seen mainly in CD169+ and MARCO+ marginal-zone macrophages; very little was in IgM+ or IgD+ B cells." (PMID 24501409, 2014). "In conclusion, our report demonstrates that similar cell surface innate immune receptors (CD36, SR-A, MARCO and TLR2) play different roles against S. aureus infection, depending on the site of infection." (PMID 24498223, 2014). "The C-lectin receptor DCSIGN, scavenger receptor MARCO and collectins were downregulated during infection but not in MDMs stimulated with hSAA-1." (PMID 37781389, 2023). "Taken together, these results demonstrate that the interaction between MARCO and GP5 may contribute to the PRRSV-induced apoptosis by which MARCO restrains PRRSV infections." (PMID 37078873, 2023). "However, in response to infection, male mice exhibited higher expression levels of CDKN1B, and CTNNB1 (KO, 1A3), TCF4 (1A0, 6A2), TAP1, and TAP2, (1A0), CDKN1A, (1A3, 6A2), MARCO, and MMP12 (1A3), CCND1, CDK2, IRF and MYC (6A2) compared to females." (PMID 32670284, 2020). "Although MARCO plays an important role initially during infection, it is believed that Cryptococcus is capable of exploiting MARCO to polarize toward a non-protective immune response." (PMID 29670625, 2018). "MARCO is involved in phagocytosis of bacteria, a step in pathogenesis that may be important in the development of PTB in the early phase of infection." (PMID 27853145, 2016).
infection (continued). "Notably, medullary and floor LECs include all the MARCO-expressing LECs in the LN, which are LN cell types predominantly targeted by CHIKV early after infection, suggesting that these changes could be due to CHIKV-MARCO interactions." (PMID 38194268, 2024). "Furthermore, analysis of LN LEC subsets at 5 days after infection reveals that, in WT CHIKV–infected MARCO–/– mice, medullary and floor LEC populations were increased compared with WT CHIKV–infected WT mice, indicating that the altered composition of LECs during CHIKV infection was MARCO dependent." (PMID 38194268, 2024). "However, by 12 hours after infection, the expression of Ccl2, Cxcl1, Cxcl9, and Cxcl10 in the dLN of WT CHIKV–infected WT mice, but not MARCO–/– mice, was significantly increased in comparison with mock-infected mice." (PMID 38194268, 2024).
cancer (29 papers, 2014 to 2025). A tumor composed of atypical neoplastic, often pleomorphic cells that invade other tissues. "Meanwhile, MARCO deficiency disrupts immunosuppressive pathways and ultimately leads to enhanced anti-cancer immunity." (PMID 40695812, 2025). "Recently, studies have demonstrated that the scavenger receptor MARCO is mainly expressed by macrophages, and that higher MARCO expression is associated with the poor prognosis of many types of cancers." (PMID 34778091, 2021). "MARCO is reputed to be a marker of a TAM subset associated with poor prognosis in human cancers." (PMID 37153595, 2023). "MARCO gene expression is normally associated with immunosuppressive pathways, enabling the establishment and persistence of solid tumors as well as metastasis in cancer." (PMID 33428680, 2021). "Taken together, these studies provide convincing evidence supporting MARCO as an attractive target for macrophage reprogramming, and the use of MARCO antibody immunotherapy shows promise for immunosuppressed cancers." (PMID 40385641, 2025). "Our findings, which is the first to associate MARCO with pro‐tumorigenic TAM traits in RCC, further underscore its significance in cancer." (PMID 41117057, 2025). "However, there have also been analyses from the TCGA database that suggest increased MARCO expression is associated in many cancer types with increased checkpoint molecule expression despite its association with poor prognosis, suggesting that it may be marker of immunotherapy-responsive tumors." (PMID 41301877, 2025). "This work establishes MARCO as a key regulator of MDSC-mediated immunosuppression and presents a compelling case for the inclusion of MARCO as a therapeutic target in cancer immunotherapy." (PMID 40695812, 2025). "In this study, we found that MARCO gene promoter was significantly hypomethylated in cancer tissue (85.2%) in comparison to healthy oral mucosa (6.7%)." (PMID 37175405, 2023). "In the majority of cancers, macrophage expression of MARCO is correlated with an immunosuppressive phenotype." (PMID 34778091, 2021). "The mesenchymal nature of MARCO is supported by the role of MARCO in regulating the epithelial-mesenchymal transition outside the context of cancer." (PMID 34011400, 2021). "Intriguingly, antibody-mediated depletion of MARCO inhibits cancer progression and metastasis, enhancing ICB efficacy, suggesting that SPP1+ macrophages play a non-negligible role in the immunorepressive response and immunotherapeutic resistance." (PMID 34354698, 2021). "Of note, MARCO is also a viable target for chimeric antigen receptor (CAR) T cell strategies for cancer therapy which has emerged as an important immunotherapeutic approach." (PMID 31805946, 2019). "MARCO is a class I scavenger receptor that mediates antibody-dependent phagocytosis of pathogen as well as of cancer cells and is expressed in M2 macrophages." (PMID 26418896, 2015). "Taken together, these data indicated that MARCO expression may play distinct roles in different cancer types." (PMID 34778091, 2021). "The literature to date on the prognostic significance of MARCO in cancer is sparse." (PMID 33194593, 2020). "Previous research on the role of MARCO in cancer has been scarce." (PMID 28673320, 2017). "In cancer patients, number of TAM-expressed SRs (CD204, MARCO, CD68, LOX-1, Dectin-1, CD206, CXCL16, Stabilin-1, CD163, and RAGE) associates with negative and more sever prognosis." (PMID 36686729, 2022). "We employed two large-scale bulk HCC RNA-Seq/microarray datasets to compare the expression of HAMP, CD5L, CETP, MARCO, and CFP between HCC and para-carcinoma tissue samples." (PMID 34001107, 2021). "In Lu and co-workers’ scRNA-Seq dataset (GSE149614), > 66% of macrophages in para-carcinoma tissue expressed CD5L, CETP, MARCO, and CFP, in contrast to < 22% of macrophages in HCC tissue." (PMID 34001107, 2021).
cancer (continued). "The pan-cancer analysis of single myeloid cells across 15 human cancer types unveiled significant findings, indicating that AMs express genes such as FABP4, MARCO, MRC1( also known as CD206), MSR1 and PPAR-γ, which are involved in self-replenishment through the secretion of (TGF-β." (PMID 38229178, 2024). "Similarly, we showed increased expression of TAM markers such as MARCO and CCR2 in metastatic biopsies as compared to primary cancer specimens." (PMID 26418896, 2015). "To validate the differential distribution of myeloid cell subtypes in other cancer types, we classified subtypes of myeloid cells according to the clustering of sub-spot GEPs in HCC tissues, including monocytes, TGFB1+ macrophages (Macro-TGFB1), Macro-SPP1, and MACRO+ macrophages (Macro-MARCO)." (PMID 36806082, 2023). "Among them, many international cohorts of cancer patients have shown negative prognostic value for TAMs expressing CD68, CD163, CD204, CD206, MARCO, and stabilin-1." (PMID 39516356, 2024). "From a functional perspective, a couple of markers demonstrated interesting biology (MARCO and ADAMDEC1) deserve more in-depth investigation, especially validation in other cancers and non-cancer-related disease, disorders and syndromes." (PMID 31467500, 2019).
bacterial infection (11 papers, 2011 to 2022). "We next evaluated the impact of MARCO deficiency on DC activation, using LPS as a surrogate for Gram(−) bacterial infection or adjuvant-supplemented vaccination." (PMID 25089703, 2014). "We showed that MARCO and phagocytosis were downregulated in hemin-treated macrophages, implicating RBC-derived iron in the susceptibility of COPD patients to bacterial infection." (PMID 34944755, 2021). "MARCO is expressed on subsets of macrophages and dendritic cells; it upregulates on macrophages after bacterial infection, and an important role for this bacteria-binding molecule is suggested in the removal of pathogens." (PMID 34572315, 2021). "MARCO is a scavenger receptor that enables recruitment of mononuclear cells and pro-inflammatory cytokine production in response to bacterial infection." (PMID 31417606, 2019). "MARCO −/− mice have severely impaired ability to clear bacteria from the lungs and increased mortality during bacterial infection, possibly due to impaired Th1 polarization." (PMID 25868721, 2015). "Whereas SRA expression is regulated primarily by factors associated with macrophage differentiation (e.g. GM-CSF) and lipid accumulation, MARCO is primarily regulated by inflammation and bacterial infection." (PMID 23617307, 2013). "Recent studies have suggested that the scavenger receptor MARCO (macrophage receptor with collagenous structure) mediates activation of the immune response in bacterial infection of the central nervous system (CNS)." (PMID 21299846, 2011). "In addition, MARCO can be upregulated on macrophages after bacterial infection suggesting its role in removing pathogens." (PMID 35717488, 2022). "This is consistent with data demonstrating MARCO activation after bacterial infection." (PMID 34572315, 2021). "In addition, IL-6 mediated increased surface expression of MARCO on macrophage enhancing their phagocytic capacity during secondary bacterial infection." (PMID 32038632, 2019). "In addition, IL-6 has been shown to improve bacterial phagocytosis by up-regulating MARCO surface expression in macrophages during secondary bacterial infection." (PMID 32038632, 2019). "Consequently, the scavenger receptor MARCO is down-regulated, and innate defense against secondary bacterial infections is suppressed." (PMID 21901097, 2011).
cardiovascular disease (2 papers, 2018 to 2021). "Macrophage scavenger receptor 1 (MSR1) and macrophage receptor with collagenous structure (MARCO) are scavenger receptors that have been implicated in lipoprotein metabolism and cardiovascular disease." (PMID 30485705, 2018). "MARCO was first identified in the mouse, is an important phagocytic receptor, and belongs to the class A scavenger receptor molecules that have mostly been studied in cardiovascular disease." (PMID 34820385, 2021).
immune disorders (2 papers, 2022 to 2025). "MARCO is a surface receptor of macrophage involving in tissue inflammation and immune disorders." (PMID 36282897, 2022). "Among the four genes that were consistently upregulated in ARHL patients (FASLG, NCAM1, MARCO, and NECTIN1), FASLG was prioritized for further validation based on its strong association with immune-mediated apoptosis and its previously reported role in age-related immune dysfunction." (PMID 40971385, 2025).
neurodegenerative disease (2 papers, 2018 to 2021). A disorder of the central nervous system characterized by gradual and progressive loss of neural tissue and neurologic function. "MARCO and other scavenger receptors may play a role in Alzheimer’s and other neurodegenerative diseases, where the receptors facilitate uptake of amyloid beta and induce an inflammatory response that could contribute to microglial neurotoxicity." (PMID 29922241, 2018).
hematological malignancies (1 paper, 2022). "Furthermore, MARCO expression in hematological malignancies should be examined in order to demonstrate how anti-MARCO treatment might be effective." (PMID 35978372, 2022).
MARCO also shares sentences with these, for which no sentence is quoted: asbestosis (3 papers); infectious disease (3); metastatic melanoma (3); chronic obstructive pulmonary disease (2); gastric cancer (2); adenocarcinoma (1); adenoma (1); adrenocortical carcinoma (1); age (1); amyloidosis (1); bladder cancer (1); brain cancer (1); cervical cancer (1); cervical intraepithelial neoplasia (1); cholangiocarcinoma (1); cholangitis (1); Chronic colitis (1); colorectal cancer (1); cutaneous sarcoidosis (1); Diabetes (1); endometrial cancer (1); endotoxemia (1); esophageal cancer (1); Hepatitis (1); hypothyroidism (1); IgG4-Related Disease (1); inflammation (1); inflammatory skin disease (1); intestinal cancer (1); leukemia (1).
A further 17 diseases each share a sentence with MARCO in 1 paper.